TPO (thyroid peroxidase)
Diseases named in the same sentence as TPO in open-access papers (continued):
Sharing a sentence is not in itself a finding about the gene and the disease.
goiter (continued). "Upon endocrinology, follow-up one week post-discharge, mild thyromegaly was noted along with positive thyroid peroxidase (TPO) at >600 IU/mL (<35 IU/mL), suggesting an autoimmune component to her symptoms." (PMID 38813074, 2024). "The isoflavones in soy can inhibit the thyroid hormone synthesis‐related enzyme TPO, contributing to goiter incidence." (PMID 37773715, 2023). "The positive rates of subclinical hypothyroidism, goiter, TPO Ab and TG Ab in female adults (35.28%, 3.39%, 13.54%, 13.94%) were higher than those in male adults (23.58%, 0.96%, 6.266%, 4.79%)." (PMID 37745704, 2023). "We also identified a new homozygous deletion in the TPO gene in one infant (F27) presenting moderate CH with goiter." (PMID 34248839, 2021). "Together with another TPO mutation, p.Glu337Lys was previously reported in a patient with a PIOD and goiter and showed residual activity towards guaiacol oxidation." (PMID 35002963, 2021). "Cases of CH due to TPO genetic defects are usually inherited in an autosomal recessive manner and are often manifested as permanent CH and goiter." (PMID 35002963, 2021). "Here, we report retrospectively on the long-term follow up (up to 43 years) of 33 patients with TPO mutations and evaluate the effect of TSH serum levels on goiter development." (PMID 34501348, 2021). "All mutations of TG and TPO, which are associated with TDH, were found in patients with PCH, 86.49% of whom had goiter." (PMID 32565793, 2020). "A subsequent cross-sectional study, published in 2010, assessed the frequency of goiter, anti-TPO antibody titers, urinary iodine, and thyroid-stimulating hormone (TSH) in 128 school children (aged 5–15 years) in Bogotá and Chía (Cundinamarca)." (PMID 31061736, 2019). "RT-PCR analysis showed that the mRNA levels of Tg and TPO expression in thyroid tissues of the goiter model group were both higher than those in normal group (P < 0.05)." (PMID 28713435, 2017). "A severe phenotype resulting in mental retardation and a large goiter has been reported in untreated patients with a complete defect of TPO gene." (PMID 26761947, 2016). "The prevalence of goiter decreased from 35.1 to 29.4 % (p = <0.001), while the prevalence of positive anti-TPO Abs decreased from 3.9 to 2.9 % (p = 0.022)." (PMID 27833458, 2016). "In a previous report, an interaction between the HLA-DRB4 and cytotoxic T-lymphocyte associated antigen 4 (CTLA-4) genes was shown to determine the thyroid function of TPO-positive Japanese HT patients with goiter." (PMID 23522401, 2013). "Two 13 year old girls had severe primary hypothyroidism (total T4 14.2 nmol/L with TSH 468 miU/L and total T4 7.7 nmol/L with TSH 183 miU/L) accompanied by goiter and positive thyroid peroxidase antibodies." (PMID 22551356, 2012). "In fact, the combination of CH, goiter and a positive perchlorate test indicating iodide organification defect should first remind one of the possibility of dyshormonogenesis due to a TPO defect." (PMID 21274344, 2010). "Patients with goiter and normal TPO antibodies should be carefully evaluated." (PMID 40665986, 2025). "The most frequently cited determinant was the patient’s TSH level (32, 11.4%), followed by clinical symptoms (18, 6.4%) and adherence to guidelines (14, 5.0%), with other considerations such as TPO-Ab status, T4 level, and goiter presence each mentioned by around 11 (4.0%)." (PMID 40926921, 2025). "The percentages positivity of TPO Ab, TG Ab, goiter was 9.80%, 9.20%, 2.10%, respectively." (PMID 37745704, 2023). "The detection rates of subclinical hypothyroidism, and goiter were significantly higher in females (35.28%, 3.39%) than those in males (23.58%, 0.96%) (P < 0.05), and the positive rates of TPO Ab and TG Ab were significantly higher in females (13.54%, 13.94%) (P < 0.05)." (PMID 37745704, 2023). "Subclinical hypothyroidism, goiter, TPO Ab, and TG Ab were more common in female than in male." (PMID 37745704, 2023).
goiter (continued). "To explore whether HYD can reduce the degree of goiter by affecting the synthesis of thyroid hormone, we tested the serum levels of Tg and TPO and the levels of Tg, TPO, and Sodium Iodide Symporter (NIS) mRNA expression in thyroid tissues." (PMID 34567211, 2021). "Other factors were also evaluated, including the development of eating habits and salt intake, prevalence of goiter, thyroid function and thyroid autoimmunity parameters (anti-TPO titers, anti-thyroglobulin antibodies (anti-Tg), and TSH receptor antibodies (TRAb)), and intelligence quotient (IQ)." (PMID 31061736, 2019). "Additionally, the direct action of the mutant TPO protein contributes to the formation of goiter." (PMID 40665986, 2025). "In family members without TPO mutations, there was no predisposition to developing a goiter." (PMID 34501348, 2021). "However, autoimmune antibodies, namely thyroid peroxidase (TPO) and anti-thyroglobulin (Tg) antibodies, can be absent in 20–50% of patients, highlighting the diagnostic value of thyroid US in evaluating patients who present with goiters." (PMID 36335310, 2022). "It has been reported that flavonoids can interfere with thyroperoxidase (TPO) activity, reducing TH synthesis with subsequent raise of thyroid-stimulating hormone (TSH) levels and potential development of goiter." (PMID 32397091, 2020). "The prevalence of goiter, TSH levels, urinary iodine, and anti-TPO among other parameters were evaluated." (PMID 31061736, 2019). "For newborns with significant goiter, elevated TSH levels, increased FT3/FT4 ratios, elevated Tg levels, and normal anti-TPO and anti-Tg levels, genetic testing should be performed to confirm the diagnosis as it helps diagnose TPO deficiency and differentiate it from other types of CH." (PMID 40665986, 2025). "And other researchers showed that some flavonoids were capable of inhibiting thyroid peroxidase activity and iodide organification by different mechanisms, capable of reducing serum T3 and T4 levels and increasing TSH levels, even leading to thyroid gland growth or goiter." (PMID 38771770, 2024). "Finally, due to resource limitations, the anti-TPO antibody was not measured for determining the autoimmune background of the thyroid dysfunction and an ultrasound examination of the thyroid gland was not performed for assessing thyroid nodules or goiter in this study." (PMID 38053115, 2023). "Twelve TPO positive women had palpable thyroid glands and 5 PPT positive women and two TPO positive, PPT negative, women had visible goiters." (PMID 25405057, 2014).
diabetes (42 papers, 2009 to 2025). "The relative risk of thyroid dysfunction associated with TPO-Abs at diabetes onset was substantially higher in adults compared with youth (RR 12.6, 95% CI 6.10–25.81 vs. RR 3.4, 95% CI 1.35–8.71)." (PMID 41255538, 2025). "In adults, most thyroid dysfunction cases were associated with TPO-Abs positivity at diabetes onset." (PMID 41255538, 2025). "TPO-Abs at diabetes onset were significantly associated with thyroid dysfunction (RR 8.1, 95% CI 4.79–13.69, p<0.001)." (PMID 41255538, 2025). "AIDs were associated with female gender, older age, longer diabetes duration, self-reported color-race (White and Brown), geographic region (lower OR for Brazilian North/Northeast region) and anti-TPO levels ≥ 35 UI/mL." (PMID 38297335, 2024). "Type 1 diabetes mellitus (T1DM) is associated with an autoimmune reaction to thyroid antigens including thyroid peroxidase (anti-TPO) and thyroglobulin (anti-Tg)." (PMID 19824863, 2009). "Hierarchical multivariate analysis, showed that AIDs were associated with female gender, older age, and longer diabetes duration, self-reported color-race (White and Brown), geographic region (Brazilian North/Northeast region) and higher anti-TPO levels (≥ 35 UI/ml)." (PMID 38297335, 2024). "Here, we report the 30-year predictive value of TPO-Abs in the same cohort and evaluate the effect of age at diabetes onset, with the aim of suggesting an evidence-based screening strategy." (PMID 41255538, 2025). "TPO-Abs were measured at diabetes onset, and thyroid function was periodically assessed throughout follow-up." (PMID 41255538, 2025). "First, the measurement of TPO-Abs at diabetes diagnosis using a semiquantitative hemagglutination assay, reflecting the technology available at that time, but less sensitive than current immunoassays." (PMID 41255538, 2025). "Thyroid dysfunction and TPO-Abs positivity in all patients and according to age at diabetes onset (<18 vs ≥18 years)." (PMID 41255538, 2025). "Data from the National Health and Nutrition Examination Survey (NHANES III) in the United States revealed that individuals with diabetes are more prone to thyroid dysfunction, especially those with thyroid peroxidase antibodies (TPOAb)." (PMID 38813351, 2024). "The presence of AIDs was associated with female gender, older age, self-reported color-race (White and Brown), longer diabetes duration, region of the country (North/Northeast) and anti-TPO ≥ 35 UI/mL." (PMID 38297335, 2024). "Moreover, TPO-Abs at diabetes onset strongly predicted the subsequent development of thyroid dysfunction over the 30-year follow-up period (log-rank test: χ2=128.3; 95% CI 4.60–9.40; p<0.001)." (PMID 41255538, 2025). "TSH and TPO-Abs should be measured at diabetes diagnosis in all patients." (PMID 41255538, 2025). "At diabetes diagnosis, 21.9% of patients were TPO-Abs positive." (PMID 41255538, 2025). "Distribution of the anti-TG and anti-TPO levels according to control, Type-I and Type-II diabetes." (PMID 40735558, 2025). "Thus, at the onset of T1DM, once the child is clinically stable, National and International Guidelines for Diabetes Management recommend screening for anti-thyroid peroxidase and anti-transglutaminase antibodies, TSH, and free T4." (PMID 39845243, 2024). "A cross-sectional study with 11,224 euthyroid subjects in Brazil presented that NC was not related to TSH in men, even before the adjustment for age, sex, race, education, thyroid peroxidase antibody, diabetes, cardiovascular disease, glomerular filtration rate, and lifestyle." (PMID 33986799, 2021). "Although, anti-TPO antibodies directed at microsomes and released from damaged thyroid cells were found in all HE cases, they have also been found in autoimmmue diseases ranging from type 1 diabetes mellitus to rheumatoid arthritis, even in euthyroid individuals." (PMID 22126669, 2011).
diabetes (continued). "Based on those findings, we proposed a strategy in which TPO-Abs should be determined at diabetes diagnosis, with annual TSH evaluation only in TPO-Abs positive patients." (PMID 41255538, 2025). "This study aimed to determine the long-term predictive value of thyroid peroxidase antibodies (TPO-Abs) at the onset of type 1 diabetes for the development of thyroid dysfunction and to evaluate the influence of age at diabetes onset." (PMID 41255538, 2025). "MNCs were isolated from 50 mL of peripheral blood of patients with diabetes mellitus and healthy volunteers (n = 13 each) and subjected to QQc for 7 days in serum‐free expansion media with VEGF, Flt‐3 ligand, TPO, IL‐6, and SCF." (PMID 33599112, 2021). "One-hundred-eighty T1DM patients were evaluated for age, duration of diabetes (DDM), positivity to TPO Antibody (TPOA), GAD Antibody (GADA), IA2 Antibody (IA2A) and fasting serum C-peptide (FCP) according to diagnosis of TD." (PMID 27011770, 2016). "In our cohort, thyroglobulin autoantibodies were measured at diabetes diagnosis, but since they proved less sensitive than TPO-Abs in our previous report, we did not analyze them during follow-up." (PMID 41255538, 2025). "After 30.7 ± 4.5 years of follow-up, 92.5% of adults negative for TPO-Abs at diabetes onset remained euthyroid, compared with only 5.6% of those who were positive (log-rank: χ2=131.5; 95% CI 3.92–8.09; p<0.001)." (PMID 41255538, 2025). "Only one patient with persistently negative TPO-Abs developed thyroid dysfunction: a case of subclinical hypothyroidism in a 29-year-old woman, 10 years after diabetes onset, identified during evaluation of secondary amenorrhea." (PMID 41255538, 2025). "However, the clinical and laboratory indicators between LADA and T2D patients were basically the same, except for family history of diabetes (P = 0.033), HDL-C value (P = 0.018) and the positive rate of TPO (P = 0.029), and Tg (P = 0.003)." (PMID 35242878, 2022). "Non-diabetes autoantibodies were detected in 20/44 (45%) 3-Screen positive patients who were positive for at least one thyroid autoantibody (TPO Ab and/or Tg Ab and/or TSHR Ab), while none were positive for the adrenal autoantibody 21-OHAb." (PMID 34533636, 2022). "Nonetheless, research including 179 children with diabetes found that 2.8% of the cohort had another AID at the time of the T1DM diagnosis, and 15.6% of the group tested positive for additional autoantibodies (anti-transglutaminase, anti-thyroglobulin, or anti-thyroid peroxidase antibodies)." (PMID 39845243, 2024).
Thrombocytopenia (41 papers, 2016 to 2026). A reduction in the number of circulating thrombocytes. "Around 2000, the development of both agents in the West was discontinued due to concerns about the formation of antidrug antibodies that cross-reacted with endogenous TPO, causing thrombocytopenia." (PMID 41403445, 2025). "We identified 6 individuals who were treated with TPO-RA for thrombocytopenia associated with HER2-targeted ADC." (PMID 37335880, 2023). "To this end, we next examined the effect of exogenous supply of TPO in vivo on thrombocytopenia caused by excessive serine." (PMID 37055385, 2023). "Nevertheless, studies on dose reduction, maintenance, and even discontinuation of TPO-RAs in treating those with refractory and severe hepatitis-associated thrombocytopenia are necessary." (PMID 37635907, 2023). "We report a series of cases in which TPO-RA was successfully utilized to treat such thrombocytopenia associated with T-DM1 and T-DXd therapy." (PMID 37335880, 2023). "The 6 cases reported here demonstrate the efficacy of TPO-RA in alleviating thrombocytopenia caused by T-DXd and T-DM1." (PMID 37335880, 2023). "This article reports a series of cases in which TPO-RA were successfully utilized to treat such thrombocytopenia associated with ado-trastuzumab emtansine(T-DM1) and fam-trastuzumab deruxtecan (T-DXd) therapy." (PMID 37335880, 2023). "The efficacy of TPO-RAs in hepatitis-associated thrombocytopenia has been widely recognized in clinical trial studies." (PMID 37635907, 2023). "With the introduction of medical alternatives such as TPO-RAs, the use of splenectomy has declined and is generally reserved for steroid-refractory patients with profound thrombocytopenia and high bleeding risk." (PMID 32710167, 2020). "Withdrawing or pausing effective ITP therapy, such as TPO‐RAs, should be avoided due to the risk of rebound thrombocytopenia (C21, 78%), and the need to maintain a haemostatic platelet count during acute thrombotic events to enable appropriate antithrombotic treatment (C22, 85%)." (PMID 40909397, 2025). "To determine whether this occurs in other infections that cause liver inflammation, we assessed TPO expression in mice infected with the protozoan parasite Leishmania donovani which also induces thrombocytopenia." (PMID 41296814, 2025). "The pros and cons need to be weighed in the use of TPO-RAs on patients with transient CIT because they usually do not require treatment for CIT unless they develop bleeding in association with the CIT or they have profound nadir thrombocytopenia (typically a platelet count <20–30 × 109/L)." (PMID 41403445, 2025). "Avatrombopag (AVA) is an oral TPO-RA whose efficacy in treating thrombocytopenia in haematological malignancy has been barely addressed." (PMID 41827460, 2026). "The objective of this study was to compare and rank the efficacy and safety of different thrombopoietin receptor agonists (TPO-RAs) in the treatment of chemotherapy-induced thrombocytopenia (CIT) among patients with solid tumors." (PMID 41403445, 2025). "Sources of heterogeneity, specifically the type of TPO-RA, the grade of thrombocytopenia, the different number of cancer types, and the duration of TPO-RA treatment of each study were explored but, failed to reach statistical significance (p > 0.05)." (PMID 38155484, 2025). "The pooled results demonstrated that these three TPO-RAs greatly reduced the incidence of grade 3 or 4 thrombocytopenia." (PMID 41403445, 2025). "There are at least six ongoing clinical trials, testing the use of TPO‐RA in the realm of post‐transplant thrombocytopenia and poor graft function." (PMID 41254453, 2025). "Patients with higher thrombocytopenia grades seem to benefit more from TPO-RA treatment and transition closer to normal platelet levels post-administration, specifically when using romiplostim for this group." (PMID 38155484, 2025).